MAPK14 (mitogen-activated protein kinase 14)
Diseases named in the same sentence as MAPK14 in open-access papers (continued):
Sharing a sentence is not in itself a finding about the gene and the disease.
Sepsis (29 papers, 2012 to 2025). Sepsis is defined as life-threatening organ dysfunction caused by a dysregulated host response to infection. "By measuring the expression levels of MAPK14 in peripheral blood samples, clinicians can potentially identify patients at risk of developing sepsis or those in the early stages of the disease." (PMID 40184094, 2025). "Among them, MAPK14 demonstrated the highest predictive performance for sepsis (AUC = 0.983), suggesting its potential as a sensitive marker for detecting sepsis-related changes and its involvement in the underlying mechanisms of the disease." (PMID 40299574, 2025). "The diagnostic test showed that serum MAPK14 had excellent performance in diagnosing sepsis, with AUROC of 0.877." (PMID 35844488, 2022). "Third, the population in this study was children, and the diagnostic value of MAPK14 in adults with sepsis needs further validation." (PMID 35844488, 2022). "Therefore, the novel sepsis biomarkers associated with metabolism, including MAPK14 have the potential to develop targeted therapies for sepsis." (PMID 37180171, 2023). "The dysregulation of MAPK14 in neutrophils during sepsis progression highlights its potential as a therapeutic target." (PMID 40184094, 2025). "Further, MAPK14 has been reported to have considerable value in the early diagnosis of sepsis in children." (PMID 40299574, 2025). "In the present study, we identified 5 lipid metabolism-related hub genes (MAPK14, EPHX2, BMX, FCER1A, and PAFAH2) that have the possibility of diagnostic and therapeutic in patients with sepsis by machine learning analysis." (PMID 37180171, 2023). "Using bioinformatics techniques, we identified PID1, CS, CYP1B1, FLVCR1, IFIT2, and MAPK14 as six MRGs that are essential in the course of sepsis." (PMID 37398680, 2023). "The serum levels of pro-inflammatory cytokines IL-1β, IL-6, and TNF-α were significantly increased after sepsis, and down-regulated by inhibiting MAPK14 to 56.7%, 64.8%, and 72.6% compared with the sepsis group, respectively." (PMID 37180171, 2023). "First, the inhibitory effectiveness of SB203580 on MAPK14 was confirmed in myocardial tissue of sepsis rats by gel electrophoresis." (PMID 37180171, 2023). "The myocardial fibers were disorganized, and the space between fibers was widened after sepsis, and these changes were ameliorated by inhibiting MAPK14 as the HE staining shown." (PMID 37180171, 2023). "To explore the effect of MAPK14 antagonism on myocardial function in sepsis, we observed the structural changes of myocardial fibers in sepsis rats." (PMID 37180171, 2023). "Considering the importance of this pathway for sepsis and ferroptosis, we chose these key ferroptosis-related DEGs for subsequent analyses: MAPK14, VEGFA, TGFBR1, and DUSP1." (PMID 36188533, 2022). "Regarding pro-apoptotic genes, sepsis increased mitogen activated protein kinase 14 (MAPK14) in OVR females and tumor necrosis factor- α (TNF-α) in control females." (PMID 35322092, 2022). "In short, there was an eminent value of MAPK14 in the diagnosis of sepsis in children, while HMXO1 and TLR4 still need to be further explored in children." (PMID 35844488, 2022). "Ferroptosis-related gene MAPK14 is of considerable value in the early diagnosis of sepsis in children." (PMID 35844488, 2022). "MAPK14 concentrations were significantly higher in children with sepsis than in controls (median 96.418 vs. 20.177 ng/ml, P < 0.001), whereas HMOX1 (P = 0.367) and TLR4 (P = 0.506) were not significantly different." (PMID 35844488, 2022). "The AUROC of MAPK14 in the diagnosis of sepsis was 0.935 (95% CI 0.894–0.975), and the corresponding sensitivity and specificity were 0.827 and 1, respectively." (PMID 35844488, 2022). "This study showed that ferroptosis-related gene MAPK14 was of prominent value in the early diagnosis of sepsis in children." (PMID 35844488, 2022). "Meanwhile, miR-128-3p enhances the protection of dexmedetomidine against ALI in sepsis mice by targeting and dampening MAPK14." (PMID 34092219, 2021).
Sepsis (continued). "Mapk14, a potential sepsis-related positive regulator gene, may contribute to sepsis through ferroptosis and senescence." (PMID 40299574, 2025). "Targeting MAPK14 could help restore neutrophil function and mitigate the excessive inflammatory response observed in sepsis." (PMID 40184094, 2025). "Additionally, THCQ has been found to regulate critical target genes in sepsis patients (such as MAPK14, MAPK3, MMP9, STAT3, and LYN), which play key roles in cellular inflammatory responses, especially through the modulation of the MAPK and Nrf2 pathways." (PMID 40963685, 2025). "The nomogram illustrates the individual contributions of the five genes (TXN, MAPK14, WIPI1, CD82, and NEDD4) and clinical information (age, gender) to the overall risk score, providing a practical tool for estimating the probability of sepsis." (PMID 40299574, 2025). "MAPK14 can be induced by many proinflammatory cytokines and is considered as a good predictor for sepsis, which is consistent with other bioinformatics analyses of sepsis." (PMID 37180171, 2023). "Importantly, we identified six critical genes, including CS, CYP1B1, FLVCR1, IFIT2, MAPK14, and PID1, which showed favorable diagnostic value in screening sepsis samples from normal samples." (PMID 37398680, 2023). "The protective effect of inhibiting MAPK14 on sepsis indicated that these lipid-metabolic hub genes might have great potential in prognosis prediction and precise treatment for sepsis patients." (PMID 37180171, 2023). "But the mechanism of the protective effect of MAPK14 on monocyte differentiation and sepsis induced cardiac dysfunction was still unknown, and will be investigated in the future." (PMID 37180171, 2023). "Moreover, miR-128-3p facilitates the protection of dexmedetomidine against ALI in sepsis mice by dampening MAPK14." (PMID 34092219, 2021). "Therefore, further study of MAPK14 about function in the pathophysiology of sepsis is needed to confirm our hypothesis." (PMID 40184094, 2025). "In addition, the role of MAPK14 in the development of sepsis was validated in vivo and in vitro." (PMID 37180171, 2023). "The hub gene MAPK14 might be critical in regulating the differentiation and function of monocytes as MAPK14 was found to be involved in all the states of monocytes along the timeline during sepsis progression, and therefore, MAPK14 might become a novel therapeutic target for sepsis." (PMID 37180171, 2023). "Finally, we validated the role of MAPK14 in sepsis patients, rats, and LPS-induced cardiomyocytes." (PMID 37180171, 2023). "Moreover, CEBPB and has-miR-150 might function in neonatal sepsis separately through targeting MAPK14 and BCL11B in the regulatory networks." (PMID 30497506, 2018). "The expression levels of CTSD (P < .001), GADD45A (P < .001), MAPK14 (P < .001), MMP9 (P < .001), and VIM (P < .001) were significantly higher in patients with sepsis than in normal healthy controls." (PMID 40184094, 2025). "This study has identified 5 key genes – CTSD, GADD45A, MAPK14, MMP9, and VIM – that are significantly upregulated in sepsis patients compared to healthy controls." (PMID 40184094, 2025). "Five hub genes including CTSD, GADD45A, MAPK14, MMP9, and VIM were upregulated in patients with sepsis compared with normal controls in the GSE28750 (peripheral blood samples) and GSE64457 (neutrophil samples) datasets." (PMID 40184094, 2025). "Patients with sepsis had a significantly higher expression of CTSD, GADD45A, MAPK14, MMP9, and VIM than normal health controls." (PMID 40184094, 2025). "The merged dataset (GSE57065 and GSE65682) revealed that all five genes (CD82, MAPK14, NEDD4, TXN, and WIPI1) were significantly upregulated in the sepsis group compared with the control group." (PMID 40299574, 2025). "We established a sepsis rat model using CLP and administered them with a MAPK14 antagonist SB203580." (PMID 37180171, 2023).
Sepsis (continued). "We found that the expression of MAPK14 and CYP1B1 was distinctly increased in sepsis samples compared with normal samples, while the expression of PID1, CS, FLVCR1, and IFIT2 was distinctly decreased in sepsis samples compared with normal samples." (PMID 37398680, 2023). "The present study analyzed different ferroptosis-related DEGs in sepsis and healthy controls and explored the clinical value of three hub genes (HMOX1, MAPK14, TLR4) in the early diagnosis of sepsis." (PMID 35844488, 2022). "In the two groups of different expression trend modules, the core genes such as CD160, GATA2, GNLY, IL2RB and TGFBR3 were downregulated in the sepsis group, while genes such as ELANE, IL1R1, TLR5, FCGR1A, MAPK14 and PCSK9 were upregulated." (PMID 35332254, 2022). "HMOX1, MAPK14, and TLR4 were significantly overexpressed in sepsis, compared with the control group (all P < 0.001)." (PMID 35844488, 2022). "The AUROC for the diagnosis of sepsis for HMOX1 and TLR4 ranged from 0.77 to 0.81, while the AUROC of MAPK14 reached 0.935 and 0.941 in the training and validation sets." (PMID 35844488, 2022). "Collectively, FFAR2, MAPK14, LTB, SAMD9L shown dysregulation in all three studies, indicating their roles at both cellular and system-level responses to sepsis." (PMID 30086151, 2018). "For example, TXN and MAPK14 are expressed predominantly in monocytes, whereas WIPI1, CD82, and NEDD4 exhibit variable expression in T and B cells, highlighting the diversity and composition of immune populations during sepsis." (PMID 40299574, 2025). "Finally, we collected 15 sepsis samples and 15 normal samples and performed RT-PCR to examine the expression of CS, CYP1B1, FLVCR1, IFIT2, MAPK14, and PID1 in our cohort, which further confirmed our previous findings." (PMID 37398680, 2023). "The results of RT-PCR indicated that MAPK14 and CYP1B1 were highly expressed in sepsis samples." (PMID 37398680, 2023). "The results indicated that 8 genes (MAPK14, MAPK8, TLR4, MAP3K5, CYBB, DUSP1, MAPK1 and ATM) might be closely related to the occurrence of sepsis." (PMID 36117534, 2022). "We identified four ferroptosis-related genes (MAPK14, VEGFA, TGFBR1, DUSP1) that may influence the pathological progression of sepsis and the resulting organ dysfunction." (PMID 36188533, 2022). "In addition, we constructed a Cox proportional hazard model using MAPK14, VEGFA, TGFBR1, and DUSP1: they influenced survival within 28 days in sepsis patients, which emphasizes their importance in sepsis pathogenesis." (PMID 36188533, 2022). "Taken together, diclofenac, flurbiprofen, and N-acetyl-L-cysteine may regulate ferroptosis and cellular-senescence-related pathways through specific binding to MAPK14, TXN, and NEDD4, thus providing potential pharmacological intervention strategies for sepsis treatment." (PMID 40299574, 2025). "No studies have shown that MAPK14, VEGFA, TGFBR1 and DUSP1 regulate ferroptosis in sepsis." (PMID 36188533, 2022).
COVID-19 (28 papers, 2020 to 2025). A disease caused by infection with severe acute respiratory syndrome coronavirus 2. "Previous studies have identified MAPK14 as a potential target for COVID-19 treatment, as MAPK inhibitors have demonstrated promise in mitigating host damage caused by virus-induced inflammatory responses." (PMID 39130417, 2024). "MAPK14, ACE, TLR4, and MAPK8 genes are present in all the compounds, and these genes are associated with COVID-19 pathways." (PMID 36144690, 2022). "Bioactive compounds in this plant target the significant COVID-19 responsible receptors such as MAPK14, ACE, TLR4, and MAPK8, which makes this plant an ideal candidate for treating this deadly infection." (PMID 36144690, 2022). "TNF, GAPDH, MAPK3, MAPK1, EGFR, CASP3, MAPK8, mTOR, IL-2, and MAPK14 are important targets for YQS in COVID-19 treatment." (PMID 35340244, 2022). "Our results also revealed that the mitogen-activated protein kinase family members, such as MAPK1 and MAPK14, were potential targets of 1,25(OH)2D against COVID-19/DM." (PMID 36532549, 2022). "The medications targeting MAPK signaling pathway, especially MAPK1 and MAPK14, are expected to be effective therapeutic medications for reducing COVID-19 damage to spermatogenesis." (PMID 36685935, 2022). "Drugs target on MAPK signaling pathway, especially on MAPK1, MAPK14, are expected to become effective therapeutic drugs to reduce the induction of cell senescence by COVID-19." (PMID 36685935, 2022). "Our study showed that ERK (MAPK1 protein) and P38 (MAPK14 protein) played important roles in mediating COVID-19 to induce cellular senescence through MAPK pathway." (PMID 36685935, 2022). "Mitogen-activated protein kinase 14 (MAPK14), angiotensin-converting enzyme (ACE), toll-like receptor (TLR4), and MAPK8 are the main players that are directly linked to the majority of the phytocompounds and played a major role in COVID-19-associated pathways." (PMID 36144690, 2022). "The results identified pathways associated with regulation of inflammation (MAPK14) and immunity (BTK, MBX) that may contribute to exacerbate organ damage linked with complications of COVID-19." (PMID 34907210, 2021). "Additionally, we identified genes such as MAPK14 that may participate in the pathogenesis of COVID-19 and the neurological diseases through the modulation of autophagy and inflammation." (PMID 39469068, 2024). "Molecular docking analysis revealed that the compound khellin interacts with all four COVID-19-responsible genes with significant binding energy and compounds, namely, coumarin, khellinin, khellinol, and visnagin possess significant binding energy with the COVID-19-responsible gene MAPK14." (PMID 36144690, 2022). "Employing the molecular docking and systems network pharmacological strategies to uncover the molecular mechanisms, anti-SARS-CoV2/COVID-19 effects of these potential bioactive molecules could be shown to be altered by key bioactives and some corresponding genes such as MAPK14, ACE, TLR4, and MAPK8." (PMID 36144690, 2022). "Investigations have suggested that MAPK14 and MAPK8 should be considered as potential new targets for COVID-19 treatment." (PMID 39130417, 2024). "Previous studies have shown that inhibition of p38 (MAPK14) -MAPK pathway can effectively alleviate the symptoms of COVID-19 infection, which is a promising treatment for COVID-19." (PMID 36685935, 2022). "In order to effectively lower the inhibition of COVID-19 on spermatogenesis, medications that can effectively inhibit the MAPK pathway in COVID-19 infected patients were seek, especially MAPK1 and MAPK14." (PMID 36685935, 2022). "Seven core targets of vitamin A against COVID-19, including CAT, EGFR, ICAM1, IL10, MAPK1, MAPK14, and PRKCB, have been detected." (PMID 34335237, 2021).
COVID-19 (continued). "In order to effectively reduce the inhibition of COVID-19 on spermatogenesis, we hope to find drugs that can effectively inhibit the negative effect of MAPK pathway in COVID-19 infected patients, especially for MAPK1 and MAPK14." (PMID 36685935, 2022). "For CVD + CKD + COVID-19, the targets were C3, TLR4, MAPK14, and CYBB." (PMID 34067609, 2021). "Finally, IL-6, MAPK3, MAPK1, MAPK14, MAPK8, IL-1β, CCL2, EGFR, PPARG, and NOS2 were declared key targets of XFBD for COVID-19." (PMID 35185537, 2021). "Furthermore, seven core targets of VA against COVID-19, including MAPK1, IL10, EGFR, ICAM1, MAPK14, CAT, and PRKCB were identified." (PMID 32805728, 2020). "In addition to the potential targets like the MAPK-14 inhibitors and FOS, we conducted the protein-drug interaction analysis of the shared DEGs between COVID-19 and the neurological diseases, identifying the candidate COVID-19 therapies." (PMID 39469068, 2024). "In PLWH with COVID-19, MAPK1 levels were intermediate between PLWH and HC group, whereas MAPK14 was elevated relative to PLWH but not significantly different from HCs." (PMID 40568587, 2025).
colon carcinoma (25 papers, 2012 to 2025). "MAPK14 was the most significant upstream kinase negatively regulating the formation of colitis-associated colon tumors." (PMID 31186640, 2019). "circMAPK14 expression and MAPK14‐175aa production further enhanced the inhibitory effect of MAPK14‐175aa on the proliferation and metastasis of colon cancer cells." (PMID 37070530, 2023). "It has been observed that mitogen-activated protein kinase 14 (MAPK14)/p38α helps protect colon cancer cells against the cytotoxic effects of 5-FU and irinotecan by triggering cytoprotective autophagy." (PMID 35912261, 2022). "PDE9A contributes consolidated pathways (platelet homeostasis mediated) with MAPK14 which can carry out an important role in colon cancer prognosis." (PMID 34016083, 2021). "Pharmacological inhibition of MAPK14 inhibited growth of colon cancer cell lines and colon tumour growth in mice." (PMID 26373535, 2015). "In several human colon cancer cell lines the inhibition of MAPK14 by SB202190 induced growth arrest and autophagic cell death." (PMID 26373535, 2015). "An involvement of MAPK14 in colorectal cancer has been shown in ApcMin colorectal cancer mice, which showed a significant reduction in tumour size when they were treated with the MAPK14 inhibitor SB202190 after azoxymethane induction of colon tumours." (PMID 26373535, 2015).
hepatocellular carcinoma (23 papers, 2008 to 2025). A malignant tumor that arises from hepatocytes. "Since this protein is one of most important members involved in the RAF/MEK/ERK signaling pathway, MAPK14 is associated with sorafenib, which is a drug used for the treatment of advanced renal cell carcinoma (primary kidney cancer) and advanced hepatocellular carcinoma (primary liver cancer)." (PMID 20419126, 2010). "For example, circSETD3 inhibits the growth of hepatocellular carcinoma via the circSETD3/miR-421/MAPK14 axis." (PMID 38184597, 2024). "Proteins in the first group, including AKT1, PIK3CA, MAPK3, MAPK2K1, and MAPK14, have been verified to be involved in the apoptosis of hepatocellular carcinoma cells." (PMID 36817123, 2023). "While blocking pErk in the pathway did not significantly reduce sorafenib resistance, knocking down phosphorylated mitogen-activated protein kinase 14 (pMAPK14) was found to rescue the efficacy of sorafenib in HBV-expressing hepatoma cells." (PMID 33669204, 2021). "Circ_0000567, which is originated from SETD3, inhibits the growth of hepatocellular carcinoma via serving as a ceRNA of MAPK14 through sponging miR-421." (PMID 32493490, 2020). "The activation of MAPK14 is involved in the multidrug resistance of hepatocellular carcinoma." (PMID 33021963, 2020). "A recent study showed that sorafenib resistance in hepatocellular carcinoma cells may at least partly be related to p38α (MAPK14)-dependent MEK-ERK activation, but other downstream proteins, such as STAT3, also seem to be important." (PMID 25665527, 2015). "MAPK14 activation has a crucial function in drug resistance in hepatocellular carcinoma (HCC)." (PMID 36740668, 2023). "We investigated MAPK14-dependent resistance to sorafenib in hepatocellular carcinoma (HCC)." (PMID 33021963, 2020).